MTOR (mechanistic target of rapamycin kinase)
Diseases named in the same sentence as MTOR in open-access papers (continued):
Sharing a sentence is not in itself a finding about the gene and the disease.
colorectal cancer (continued). "In colorectal cancer, PUS7 facilitates cancer cell migration through the HSP90/PUS7/LASP1 pathway, enhances proliferation via SIRT1 activating the Wnt/β-catenin pathway, and stimulates proliferation and invasion through the PI3K/AKT/mTOR signaling pathway." (PMID 41554761, 2026). "In lung and colorectal cancer models, CLZ has been found to affect important oncogenic pathways such as PI3K/protein kinase B (Akt) and adenosine monophosphate-activated protein kinase (AMPK)/mammalian target of rapamycin (mTOR), leading to tumor suppression." (PMID 41341097, 2026). "Here, we found that the overexpression of PRMT5 increased the proliferation of colorectal cancer cells and that the effect of PRMT5 on colorectal cancer cell proliferation was reversed by treatment with rapamycin, a selective mTOR inhibitor that suppresses the AKT/mTOR signaling pathway." (PMID 40279519, 2025). "Curcumin modulates key oncogenic pathways such as RAS-ERK, PI3K/AKT/mTOR, COX-2, NF-κB, and JAK/STAT, showing efficacy in neurofibromatosis type 1, breast, cervical, lung, esophageal, uterine, prostate, pancreatic, hepatocellular, and colorectal cancers." (PMID 41346617, 2025). "In colorectal cancer, PUS7 regulates the PI3K/Akt/mTOR signaling cascade, where PUS7 knockdown in colorectal cancer cells led to reduced phosphorylation of PI3K, Akt, and mTOR, while PUS7 overexpression enhanced their phosphorylation in colon cancer cells." (PMID 40940790, 2025). "We conducted Western blot analysis to examine the effects of phillyrin on the PI3K/AKT signaling pathway in colorectal cancer cells by assessing the levels of PI3K, p‐PI3K, AKT, p‐AKT, mTOR, and p‐mTOR, along with their downstream targets, in HT29 and HCT116 cells." (PMID 41142018, 2025). "Of course, in addition to the PI3K/AKT/mTOR pathway, other pathways may also exist in NAT1 interactions to regulate colorectal cancer glycolysis." (PMID 38916406, 2024). "The PI3K/AKT pathway plays a pivotal role in the onset and progression of colorectal cancer, influencing autophagy, apoptosis, and EMT-mediated cancer cell migration and invasion, accompanied by regulation of CCND1, mTOR, FOXO, HIF-1α, CASP, Bax, and Bcl-2 expression." (PMID 38384287, 2024). "Similarly, a ruthenium complex with 5-fluorouracil inhibited Akt/mTOR signaling, and a ruthenium-xanthoxyline complex targeted the Hsp90 chaperone in HCT116 colorectal cancer cells." (PMID 38830859, 2024). "Therefore, it can be inferred that NAT1 suppresses liver metastasis of colorectal cancer by modulating EMT and glycolysis in colorectal cancer cells through the PI3K/AKT/mTOR signaling pathway." (PMID 38916406, 2024). "In colorectal cancer models, it is known that tumor-secreted CTSK can bind to Toll-like receptor 4 (TLR4) on the surface of macrophages and promote M2 polarization through a mammalian target of rapamycin (mTOR)-dependent pathway." (PMID 38993570, 2024). "Our findings highlight that overexpression of NAT1 significantly inhibits the PI3K/AKT/mTOR signaling pathway, thereby suppressing EMT, glycolytic ability, and VEGF expression in colorectal cancer cells, collectively preventing the development of liver metastasis." (PMID 38916406, 2024). "Signal transducer and activator of transcription 3 (STAT3) is a critical transcription activator in angiogenesis; it has been reported that the JAK2/STAT3 and mTOR/STAT3 signaling pathways promote apoptosis and inhibit proliferation and angiogenesis in colorectal cancer cells." (PMID 38257275, 2024). "mTOR suppression decreased ALDH1 activity, a marker of CSCs in colorectal cancers." (PMID 37490168, 2023). "In colorectal cancer cells, upregulation of LACTB expression can inhibit the cellular EMT process and increase the expression of epithelial markers through the autophagy signaling pathway involving PI3K/AKT/mTOR." (PMID 38149985, 2023).
colorectal cancer (continued). "The mTOR inhibitor, rapamycin, targeted the mTOR–HIF-1α axis and induced colon cancer cells to become sensitive to irinotecan, both in vitro and in vivo study using a xenografted metastasis model of human colorectal cancer." (PMID 36839795, 2023). "circNOLC1 interacting with AZGP1 to activate mTOR/SREBP1 signaling, or sponging miR‐212‐5p to upregulate c‐Met expression, both of which can further induce G6PD to activate oxidative pentose phosphate pathway in colorectal cancer liver metastasis." (PMID 37870214, 2023). "Compared with colorectal cancer patients without neoCRT, post-neoCRT p-mTOR was significantly overexpressed in the rectal cancer after neoCRT." (PMID 35201501, 2022). "To confirm whether PGC-1α regulates the expression levels of LARS1, p-AKT, p-GSK-3β, p-mTOR, p-S6K1, p-4EBP1, β-catenin, c-Myc, cyclin D1, and vimentin in other colorectal cancer HT-29 and SNU-C4 cells, we performed qRT-PCR and Western blot analysis." (PMID 36612155, 2022). "Atractylenolide I (ATL-1) has been shown to be an effective drug in suppressing colorectal tumor progression, primarily by preventing colorectal cancer cell proliferation through glucose metabolism, apoptosis alteration, and stump-like behavior via the AKT/mTOR signaling pathway." (PMID 36428613, 2022). "Mechanistically, we revealed that MTERF1 regulates the AMPK/mTOR signaling pathway in cancerous cell lines, and we also confirmed the involvement of the AMPK/mTOR signaling pathway in both xenograft tumor tissues and colorectal cancer tissues." (PMID 36293209, 2022). "Here, they found that overexpression of RNH1 in colorectal cancer cells HT29 does not change mTOR protein level, however phosphor-mTOR level reduced significantly leading to increased autophagy." (PMID 33525475, 2021). "Moreover, aspirin reduces mTOR signaling by inhibiting the mTOR effectors S6K1 and 4EBP1 in colorectal cancer and suppresses esophageal squamous cell carcinoma growth by inhibiting HBXIP and HMGA2." (PMID 34414020, 2021). "In agreement with our observation, it was recently described that Met transiently inhibits colorectal cancer cell proliferation and clonogenicity through AMPK activation and increase ROS production, which suppressed the mTOR pathway and its downstream targets S6 and 4EBP159." (PMID 33854147, 2021). "Previous in vitro study in colorectal cancer cells treated with CT showed decreased cell invasion, and in vivo CT treatment decreased colorectal cancer tumor size, promoted downregulation of PI3K/Akt/mTOR signaling and inhibition of HIF-1α factor." (PMID 33544704, 2021). "Three key pathways were negatively enriched in CtBP1-KD cells, including epithelial to mesenchymal transition in colorectal cancer, MAPK signaling pathway, and cell cycle, while focal adhesion-PI3K-Akt-mTOR-signaling and integrin-mediated cell adhesion were positively enriched." (PMID 34253710, 2021). "Moreover, a potential mechanism through FASN-induced colorectal cancer proliferation and metastasis upon its regulation of the AMPK/mTOR pathway by increasing ATP production, resulted in inhibition of AMPK and activation of mTOR has been demostrated." (PMID 34421595, 2021). "Our study also proves that PRMT5 promotes cell proliferation and EMT in human colorectal cancer via activation of the EGFR/Akt/GSK3β signaling axis, but not ERK1/2 or PTEN/mTOR signaling pathways, which is strongly linked to the PRMT5 enzyme activity." (PMID 33495409, 2021). "In colorectal carcinoma, downregulation of the E3 ligase FBX8 correlated with enhanced mTOR activity and might thereby promote invasion and metastasis." (PMID 34290272, 2021). "In colorectal cancer, lithium treatment was shown to enhance the therapeutic responsiveness to chemotherapeutic agents by suppressing the activity of PI3K/Akt, an upstream regulator of mTOR, by triggering autophagy initiation." (PMID 32235551, 2020).
colorectal cancer (continued). "Furthermore, we have recently reported that an mTOR inhibitor, NVP-BEZ235, potentiated the BITC-induced apoptosis induction in human colorectal cancer cells." (PMID 31222108, 2019). "Our results suggest TKSE has potent anti-tumor effects, and that these effects might be due to the targeting of Akt/mTOR, ERK, and AMPK, induction of mitochondrial-mediated apoptosis, and suppression of colorectal cancer cell metastasis." (PMID 31624493, 2019). "The most meaningful KEGG terms for miR‐181a targets were miRNAs in cancer, MAPK, pathways in cancer, FoxO, VEGF, and colorectal cancer while the most significant KEGG terms for miR‐181b targets were HIF‐1, miRNAs in cancer, PI3K‐Akt, mTOR, FoxO, MAPK, and central carbon metabolism in cancer." (PMID 31448575, 2019). "Meanwhile, the genes participated in the screened modules of miR‐181b targets network were highly related to some vital pathways including PI3K‐Akt, miRNAs in cancer, mTOR, central carbon metabolism in cancer, HIF‐1, FoxO, pathways in cancer, and colorectal cancer pathway." (PMID 31448575, 2019). "Notably, we found that AKT/mTOR activity was significantly reduced in DDX5 knockdown colorectal cancer cell lines, but the addition of mTOR agonist (MHY1485) significantly reversed the activation of AKT/mTOR signalling pathway." (PMID 30484950, 2019). "Consistent with our findings, a previous study found that the downstream serine/threonine kinase mTOR, which is known to be an important upstream regulator of SGK1 and plays a crucial role in promoting EMT via RhoA and Rac1 signaling in colorectal cancer (CRC)." (PMID 29609629, 2018). "In summary our data revealed that colorectal cancer cell lines expressing BRAFV600E and KRASG12V are similar in terms of their morphologies and mitogenic signaling, but exhibit fundamental differences in mTOR-mediated signaling." (PMID 29907857, 2018). "We found that changing glucose levels did not affect colorectal cancer cells expressing BRAFV600E because of the decoupling of AMPK from mTOR signaling." (PMID 29907857, 2018). "Molecular analysis further revealed that PTRF inhibited the activation of the AKT/mTOR pathway, indicating that PTRF may control the progression of colorectal cancers by downregulating this signaling pathway." (PMID 27203393, 2017). "Interestingly, adiponectin inhibits the growth of cultured colorectal cancer cells in vitro via activation of adenosine monophosphate-activated protein kinase (AMPK) and suppresses the mammalian target of rapamycin (mTOR) pathway." (PMID 28422056, 2017). "To define the clinical significance of PI3K/Akt/mTOR signaling in ALDEFLUORhigh CCSCs, we initially queried the Oncomine® database for the significance of ALDH1 overexpression in the Reid colorectal cancer patient data set (Compendia Bioscience, Ann Arbor, MI)." (PMID 28881576, 2017). "Furthermore, in colorectal cancer cell lines isolated from tumors resistant to the AKI MK-8745, an increase in phosphorylation of mTOR and Akt was observed and these cells underwent apoptosis in response to mTOR and Akt inhibition." (PMID 28555173, 2017). "In three different colorectal cancer cell lines (DLD1, HCT-116 and RKO), suppression of EGFR and PIK3CA through the enhanced expression of miR-134 or -370 led to a suppression of the key molecules of the PI3K/AKT/mTOR pathway." (PMID 27095166, 2016). "Of the 41 patients with colorectal cancer without a FBXW7 mutation, 12 (29%) were enrolled on a protocol with an mTOR inhibitor and 4 (33%) had SD." (PMID 24586741, 2014). "Normal colorectal stem cells carrying the wild-type PIK3CA gene will not be affected by the inhibition of the PI3K/mTOR pathway by PF-04691502, which represents a therapeutic window for PF-04691502 treatment in colorectal cancer." (PMID 23826249, 2013).
colorectal cancer (continued). "Using the ApcMin/+ mouse model of colorectal cancer, we investigated how cachexia affects the regulation of 5′-adenosine monophosphate-activated protein kinase (AMPK), protein kinase B (Akt) and mammalian target of rapamycin (mTOR) signaling in the heart." (PMID 23589074, 2013). "For a pathway-based stratification of CRC tumor samples, we selected four pathways known to play a role in progression of CRC: MAPK signaling (KEGG: hsa04010), mTOR signaling (KEGG: hsa04150), ErbB signaling (KEGG: hsa04012), and colorectal cancer disease pathway (CRCdp, KEGG: hsa05210)." (PMID 23272949, 2012). "mTOR exists in two distinct complexes, however, no study so far has analyzed the specific role of mTORC2 in colorectal cancer development." (PMID 20226010, 2010). "Another flavonoid compound found in Citrus fruits, narigenin, might be a future candidate for the inhibition of colorectal cancer stem cells, since it down-regulates several signaling pathways (TGF-β, Notch, MAPK-ERK, PI3kinase/Akt/mTOR, JAK-STAT) and Nrf2 production." (PMID 39859345, 2025). "This discovery has clear clinical translational value, particularly in colorectal cancer patients with TSC1 pathway abnormalities, where combining mTOR inhibitors may enhance the sensitivity to immune checkpoint therapy and expand the applicability of precision immunotherapy." (PMID 41445741, 2025). "Notably, prunin, a citrus-derived flavonoid glycoside, has demonstrated potent anticancer activity by modulating the phosphatidylinositol 3-kinase/protein kinase B/mammalian target of rapamycin (PI3K/Akt/mTOR) and Wnt/β-catenin pathways in breast and colorectal cancers." (PMID 40565318, 2025). "The PI3K/Akt signaling axis is significantly activated in colorectal cancer, and enhanced PI3K/Akt signaling not only directly activates GLUT1/4, HK2, and PFKFB3/4 but also coordinates glucose metabolism, nucleotide metabolism, and amino acid synthesis via activation of the mTOR pathway." (PMID 41488637, 2025). "Specifically, we found two phosphorylation sites related to mTOR signaling, AKT1S1-S183 and TBC1D4-S588, among the pathway markers targeted in the hybrid-DIA analysis, that were statistically down-regulated in patients with colorectal cancer relapse after surgery." (PMID 40269326, 2025). "Additionally, Li’s research found that knockdown of FOXO6 could inhibit the phosphorylation of PI3K, AKT and mTOR (p < 0.01), and decrease the expressions of P-PI3K, P-AKT and P-mTOR in colorectal cancer cells." (PMID 37822879, 2023). "Epigenetic control of autophagy by methyltransferases has been reported in the setting of colorectal carcinoma where the methyltransferase EZH2 inhibits several negative regulators of mTOR (mechanistic target of rapamycin [serine/threonine]) leading to inhibition of autophagy." (PMID 35710782, 2022). "In addition, BEZ235 has been reported to inhibit cell viability and enhance the radiosensitivity of colorectal cancer (CRC) both in vitro and in vivo through the attenuation of radiation-inducing AKT/mTOR signaling activation and the inhibition of the DNA-DSB repair mechanism." (PMID 31430901, 2019). "In contrast, mTOR inhibitors appear to be more effective when combined with cytotoxic chemotherapy and in one phase I clinical trial, the combination of RAD001 with 5-fluorouracil in a refractory colorectal cancer patient population resulted in one PR lasting 7.4 months." (PMID 28060954, 2017). "In addition, cucurbitacin E also inhibits OS cell growth and invasion by suppressing PI3K/AKT/mTOR signaling, whereas a lack of oxidative phosphorylation prevents cell apoptosis in colorectal cancer and OS." (PMID 28477009, 2017).
colorectal cancer (continued). "Although our initial study focused on the mTOR pathway, further analysis of the gene set enrichment analysis offer other opportunities to look at combinatorial therapies such as oxaliplatin and a WNT inhibitor in the treatment of colorectal cancer liver metastasis." (PMID 28060954, 2017). "Finally, the percentages of PIK3CA mutations were higher in colorectal-cancer samples which had mTOR-pathway activation (9/27, 33%) than in colorectal-cancer samples without mTOR-pathway activation (6/44; 14%; χ2 p=0.0484)." (PMID 29137436, 2017). "It has been reported the PI3K/Akt/mTOR signaling components were highly activated in glandular elements of colorectal carcinoma and colorectal adenomas with high-grade intraepithelial neoplasia, indicating that inhibitors of PI3K/Akt/mTOR signaling may serve as potential anti-CRC agents." (PMID 26160839, 2015). "On the other hand, the use of some potent PI3K/mTOR inhibitors, even nonsteroidal anti-inflammatory drugs (NSAID) was thought associate with longer survival among patients with mutated-PIK3CA colorectal cancer, but not among patients with wild-type PIK3CA cancer." (PMID 25106743, 2014). "However, another study suggests that PUS7 also can activate the Wnt/β-catenin pathway by acting on Sirtuin 1 and PI3K/AKT/mTOR signaling pathway, indicating that PUS7 may simultaneously act on multiple downstream targets and promote colorectal cancer progression." (PMID 37420297, 2023). "However, to date, the benefits of everolimus in colorectal cancer have been minimal and thus suggest that monotherapy with a mTOR inhibitor may not be clinically efficacious." (PMID 28060954, 2017). "Loss of phosphatase and tensin homologue (PTEN) expression may be prognostic in colorectal cancer (CRC) and may have a correlation with vascular endothelial growth factor (VEGF) expression via hypoxia-inducible factor 1 (HIF-1) alpha, and the PI3K/mTOR pathways." (PMID 23930204, 2013). "Collectively, our findings uncover that PRMT5 controls human colorectal cancer cell proliferation via activation of Akt, but not ERK1/2 or PTEN/mTOR signaling pathways." (PMID 33495409, 2021). "It is implied that PRMT5 promotes colorectal cancer cells growth and EMT via activation of Akt, but not ERK and mTOR signaling pathway." (PMID 33495409, 2021). "Therefore, malignancy driver functions attributed in our work to p32 in colorectal cancer cells could be explained at least partly by its ability to significantly modify the transcription levels of HAS-2 and PDCD4 genes, and to its ability to activate the PI3K/Akt/mTOR signaling pathway." (PMID 34136383, 2021). "In contrast to what has been reported in breast and colorectal cancer cells, palbociclib induced a decrease in c-MYC expression, and no change in mTOR pathway activity, as assessed by p-S6 protein levels." (PMID 33572972, 2021). "A further study has shown that a combination of specific PI3K inhibitors (GDC-0941), rather than dual mTOR/PI3K inhibitors (NVP-BEZ235), with MEK inhibitors results in synergy in colorectal cancer cell lines." (PMID 25170609, 2014). "Moreover, PRMT5 controls human colorectal cancer cell proliferation via the activation of Akt, but not ERK1/2 or PTEN/mTOR signaling pathways." (PMID 33495409, 2021). "In our study, we show that PRMT5 could activate Akt in colorectal cancer cells independent of ERK1/2, PTEN, and mTOR signaling, using PRMT5 stable knockdown cell lines and specific inhibitor GSK591, which is required for PRMT5 enzyme activity." (PMID 33495409, 2021). "However, analysis of A375 melanoma cells after treatment with palbociclib revealed significant downregulation of MYC target genes, and no change in mTOR signalling or c-MYC protein, suggesting that the mechanism in melanoma cells is distinct from colorectal cancer cells." (PMID 33572972, 2021).